LAG3 (lymphocyte activating 3)
Diseases named in the same sentence as LAG3 in open-access papers (continued):
Sharing a sentence is not in itself a finding about the gene and the disease.
tumor (continued). "Consistent with the gene expression profile of tumor antigen-specific CD8+ T lymphocytes in human tumors, the majority of all CD8+ subsets displayed an exhausted profile with expression of Tox, Pdcd1, CTLA4, Lag3, and Havcr2." (PMID 35260537, 2022). "A moderate correlation was observed between frequencies of FoxP3+ Tregs and CD4+LAG-3+ T cells in PBMCs of CRC patients, and it was found to be stronger in advanced tumor stages compared to early stages (r = −0.022, p = 0.945 [early]; r = 0.488, p = 0.039 [advanced])." (PMID 36146549, 2022). "Moreover, dual blockade of LAG-3 and PD-1 can also increase the number of tumor-infiltrating CD8+ T cells and reduce Treg, thereby synergically enhancing anti-tumor immunity." (PMID 35874717, 2022). "Lymphocyte-activation gene 3 (LAG-3) is a cell surface marker predominantly expressed in CD3-positive T cells with low expression in normal or malignant B cells, NK cells, and myeloid cells 35 and in PD-1-positive CD8+ and CD4+ tumor-infiltrating lymphocytes." (PMID 35223381, 2022). "The study went on to show that, among the four g1 ILC clusters, the one most enriched in the tumor also displayed the highest expression of inhibitory receptors/exhaustion markers, such as KLRC1 (NKG2A) and LAG3, mirroring the phenotype of murine intILC1 in cancer." (PMID 36372017, 2022). "In addition, since FREM2 mutation was associated with immune infiltration, we analyzed its association with the expression levels of PDCD1, CD274, CTLA4, LAG3, TIGIT, and HAVCR2, which are important immune checkpoints responsible for tumor immune escape." (PMID 35252356, 2022). "The expression level and specificity/affinity between checkpoint receptor (LAG3) on the patients’ T cells and the checkpoint ligands (GAL-3, HLA-DP/DQ/DR) on patients’ tumor cells are a critical consideration impacting the functional sequelae of their interaction." (PMID 34290359, 2022). "In addition, LAG-3, TIGIT, and PD-1 are co-expressed on the surface of T cells and are all immune checkpoint ligands subject to tumor immunosuppression." (PMID 35892835, 2022). "To comprehensively inspect the immune microenvironment of HCC TME, we firstly compared gene expression of immune inhibitory checkpoint molecules between tumor tissues and normal (peri-tumor) tissues, including CD274, CTLA4, HAVCR2, LAG3, PDCD1, PDCD1LG2, TIGIT, and SIGLEC15." (PMID 35444645, 2022). "LAG-3 is expressed primarily on NK cells, B cells, CD4+, and CD8+ T cells, where it blocks T cell receptor signaling by binding with high affinity to MHC class II molecules, thereby decreasing anti-tumor T cell activity." (PMID 36106025, 2022). "Tumor antigen–specific T cells within the tumor microenvironment often express tissue retention markers such as CD103 and display evidence of activation and exhaustion with expression of PD-1, Tim3, Lag3, and others." (PMID 35727629, 2022). "Similar to LAG3, TIM3 results in negative regulation of T cell response, ultimately leading to T cell exhaustion, while its inhibition reduces tumor growth especially in combination with PD-1 blockade, but again the overall anti-tumor effect is modest." (PMID 36578079, 2022). "It has been suggested that the antagonistic mAb against LAG3 could blockade the interaction between LAG3 and MCH-II molecules expressed by tumor and/or immune cells, leading to the promotion of tumor cell apoptosis." (PMID 36180876, 2022). "Here, sLAG-3 was shown as a marker of tumour burden by tracking mRNA expression of the soluble isoform of LAG-3 (LAG-3V3) as opposed to the cleaved soluble form." (PMID 35265944, 2022). "Following the accomplishments of PD-1 and CTLA-4 inhibitors, others targeting TIGIT, Tim-3, Lag3 and NKG2A are currently being explored in some solid tumors in various pre-clinical and clinical trials, in order to promote effective anti-tumor immunity with clinical benefits." (PMID 36077799, 2022).
tumor (continued). "To assess whether this is indeed the case, we mapped out the kinetics of thermal pain hypersensitivity, increased frequency in intratumoral PD-1+LAG3+TIM3+ CD8+ T cells and tumour growth." (PMID 36323780, 2022). "We observed that although the dual blockade of PD-L1 and LAG-3 caused a slight boost in proliferation and IFN-γ production by CD8+ T-cells in co-culture with tumor cells, the difference was not greater than the blockade of only PD-L1." (PMID 35655709, 2022). "The results suggested that significant upregulation of T and NK cells’ surface CD39 and LAG3 expression in the tumor, which did not occur in all tumor samples but was observed in most tumor samples." (PMID 36347860, 2022). "LAG-3 is expressed by many T cell subsets, including: CD4 T helper cells, cytotoxic CD8 T cells, activated T cells, NK T cells, effector CD4 T cells, regulatory T cells, CD8 tumor-infiltrating lymphocytes and tumor-infiltrating antigen-specific CD8 T cells." (PMID 35954196, 2022). "Suppression of LAG3 showed reduced tumour growth which was not very effective, however, suppression of LAG3 and PD-1 together, not only reduced tumour growth but also increased survival rate in mice." (PMID 36551617, 2022). "Effector genes such as GZMB, GZMH and KLRG1 were the marker genes in clonotypes shared by all tissues, while the clonotypes present only in tumor showed upregulated T-cell exhaustion genes (HAVCR2, LAG3, CTLA4, TIGIT, PDCD1, and ICOS) and activation genes (SELL and TNFRSF9)." (PMID 36185254, 2022). "Moreover, other immune checkpoints, such as TIGIT, LAG-3, and TIM-3, can boost tumour immune evasion and motivate the exhaustion of virus-specific T cells." (PMID 36484006, 2022). "The objectives include tumor targeting, determination of 89Zr-DFO-REGN3767 biodistribution and dosimetry, optimal time for imaging and tumor uptake after drug administration, evaluation of tumor uptake of the 89Zr-DFO-REGN3767 and correlation with LAG-3 expression (NCT04566978)." (PMID 35755891, 2022). "Immune infiltration and immune checkpoints suggest that in cluster 1 there is an increased number of highly infiltrated CD86 and LAG3 cells, which are more active in boosting inflammation, and that CD44 has a higher activity and is more able to promote tumor metastasis." (PMID 36186475, 2022). "Moreover, we monitored the tumor development and survival in mice to assess the anti-cancer effects of MWA alone or in combination with LAG3 blockade." (PMID 36180876, 2022). "In order to confirm the status of TIRs expression upon tumor cell-mediated antigen exposure during the killing assay, gene-edited 3KO MH and OT-1 CD8+ T cells, respectively, were isolated, stained for PD-1, LAG-3, and TIM-3 and subjected to analysis by flow cytometry." (PMID 35328630, 2022). "We further revealed that ADAMTS12 expression was positively correlated with immune checkpoint proteins (such as PDCD1, CD274, LAG3, and CTLA4), immunosuppressive genes, chemokines, and chemokine receptors in most tumor types." (PMID 35280819, 2022). "Upregulation of CTLA-4 and LAG3 molecules can initiate a negative feedback mechanism that creates an active immune environment in an inflamed tumor and can improve prognosis." (PMID 35434132, 2022). "In addition, T cells also express LAG-3, TIM-3, TIGIT, and other receptors, and these immunosuppressive receptors are potential therapeutic targets and have seen anti-tumor efficacy in preclinical studies." (PMID 36225938, 2022). "Despite the differential composition of g1 ILCs in the different tumor stages, all intratumoral g1 ILCs produced lower levels of IFNγ and presented increased expression of the exhaustion markers Tigit, Pdcd1 (PD1), and Lag-3, the latter two being the most prominent in ILC1s." (PMID 36372017, 2022).
tumor (continued). "Moreover, these mice showed significantly higher levels of IFN-γ and granzyme B, as well as a lower proportion of PD1+, LAG3+ and TIM3+ in CD8+ T cells in the tumor tissue, indicating a higher level of CD8+ T-cell activation." (PMID 36451817, 2022). "The main objective of this study was to simultaneously analyze, using flow cytometry, the relative ex vivo expression of five major ICs, namely PD-1, TIGIT, Tim-3, Lag3 and NKG2A, by the CD3+ TILs of CRCs, as well as that of their ligands by the tumor cells and myeloid cells of the TME." (PMID 36077799, 2022). "Although tumour growth was not significantly inhibited by napabucasin (data not shown), LAG‐3+ and Tim‐3+ CD8+ T cells were significantly reduced, while the expression of IFNγ was significantly increased." (PMID 35665592, 2022). "The immune exhaustion score (including LAG3 and TIDE scores) was also higher in MTCS2, which indicated that a different metastatic phenotype might reverse tumor immunity and induce immune exhaustion." (PMID 38090653, 2022). "LAG‐3 is also highly expressed on CD8+ TILs, and it has been proposed that LAG‐3 may be used as an indicator of tumor prognosis and as a target for ICI therapy." (PMID 35782339, 2022). "Interestingly, both KCC2 and NKCC1 are significantly related to tumor-infiltrating immune cells, including tumor purity and immune checkpoint molecules such as PD-L1, CTLA-4, LAG-3, and TIGIT in ccRCC." (PMID 35372048, 2022). "Hot tumor is characterized by high T cell and CTL infiltration in CT and IM, high immunoscore, and suppressed T cell function due to activated immune checkpoints such as PD-1, CTLA-4, TIM3, and LAG3." (PMID 36293435, 2022). "Positive correlations were observed between levels of different immune checkpoint-expressing CD4+ T cells, including PD-1, TIM-3, LAG-3, and CTLA-4 with FoxP3+ Tregs, Helios+ T cells, FoxP3+Helios+ Tregs, and FoxP3+Helios− Tregs in the tumor microenvironment (TME)." (PMID 35455287, 2022). "LAG-3 was found to negatively regulate the mitochondrial activity in naive CD4+ T cells, restricting the normal metabolism and expansion of naive CD4+ T cells and leading to T cell exhaustion and anti-tumor response." (PMID 35958563, 2022). "However, dMMR/MSI-H CRCs also highly upregulate the expression of immune checkpoints - (i.e., PD-1 ligands, CTLA-4 ligand, LAG-3, and IDO1) that account for the suppression of an active immune response despite the high tumor infiltrating lymphocyte count." (PMID 35582524, 2022). "Successful immune escape of tumor cells includes also the production of soluble factors in the microenvironment by tumor cells (TGF-β, LDH5), the induction of co-inhibitory molecules (PD-1, LAG-3 and TIM-3) and the release of immunosuppressive factors (CSF-1, VEGF, PGE2, NO, Arg I, IDO and Gal-1)." (PMID 35603195, 2022). "For instance, single-cell RNA sequencing recently showed high expression of Lymphocyte Activating 3 (LAG3) in NKT/CD8+ T-cells in ESCC samples, supporting a potential role for anti-LAG3 treatments (a novel class of immune checkpoint inhibitors) in this tumor type." (PMID 35326673, 2022). "LAG-3 plays an important immunoregulatory role in a variety of human tumors, and blocking LAG-3 can enhance the proliferation of TILs and the secretion of cytokines, and enhance anti-tumor immunity." (PMID 35958563, 2022). "LAG3, TIM-3, and TIGIT expression seemed to be mutually exclusive within the tumor microenvironment and could be used to be define distinct tumor subtypes." (PMID 36313654, 2022). "Can tumours ectopically express LAG-3, and if so, what implications might this have for LAG-3 targeting therapies?" (PMID 35265944, 2022). "Recently, focus has shifted towards novel strategies that target LAG3 and TIM3, as well as targeting Tregs and their immunosuppressive factors (e.g. TGF-β) into the tumor microenvironment, which have been proposed as more effective in stimulating an anti-tumor immune response." (PMID 35814368, 2022).
tumor (continued). "Furthermore, TIGIT, LAG-3, HAVCR2 (TIM-3), and IDO1 are known as novel immune checkpoint targets that can suppress the activation of effector T lymphocytes, hence mediating a tumor immune escape mechanism." (PMID 35416526, 2022). "HLA-II over-expression by tumor cells and fibrinogen-like 1 (FGL1), a protein secreted by liver cells and tumor cells, are ligands of LAG-3, and their secretion impact the expression of LAG-3 in T cells, promoting an immunosuppressive function." (PMID 34447383, 2021). "High LAG3 and FGL1 expression boosts tumor growth by inhibiting the immune microenvironment." (PMID 35111155, 2021). "In addition, LAG3 and TIGIT are usually coexpressed and upregulated along with PD1 on tumor-infiltrating lymphocytes (TILs)." (PMID 34249711, 2021). "The delay in tumor growth on treatment with anti-LAG-3 mAbs alone was not significant, whereas a statistical difference was observed between anti-PD-1–treated and IC mAb–treated mice (P = 0.0201)." (PMID 33712537, 2021). "Until now, the research in this field is mostly carried out at the tumor tissue level, whether methylation statuses of PDCD-1 and LAG-3 in PBL could be involved in the anomalous expression of ICs and related to CRC risk remain unclear." (PMID 34544358, 2021). "Because activated NK cells, similarly to T cells, can express immune checkpoint molecules (e.g., PD-1, LAG-3, and TIM-3) that might inhibit NK anti-tumor responses their blockade with ICI could be envisaged in order to reinvigorate cytotoxic activity." (PMID 35069581, 2021). "Therefore, we evaluated the relationship between the expression of immune inhibitory molecules (TIGIT, PDCD1LG2, PDCD1, LAG3, HAVCR2, CTLA4, and CD274) in the immune ignorant, immune inactive, and hot tumor subtypes." (PMID 33777927, 2021). "Furthermore, the expression of SLC13A4 in HNSCC is negatively correlated with a variety of T cell exhaustion markers, including LAG3 ( p < 0.001), TIM-3( p < 0.001) and CTLA-4 ( p < 0.001), indicating its potential mechanism in regulating tumor immunity." (PMID 34840533, 2021). "Targeting tumor infiltrating Tregs may be achieved using antibodies to TIM-3, LAG-3, TIGIT, VISTA, and CD73." (PMID 34806028, 2021). "By performing differentially expressed gene (DEG) analysis, we found that many immunosuppressive and exhaustion-related genes such as LAG3, CD101, SMAD2, and ID1, which was one type of the mediators of tumor progression, were highly expressed in PBMCs from RTP patients." (PMID 34687295, 2021). "Subsequently, we evaluated the additive effect of anti-PD-1 mAb or anti-PD-L1 mAb with/without anti-Lag-3 mAb with/without anti-Tim-3 mAb in cytotoxic assay using tumor-antigen specific CTL clones against GC cell lines." (PMID 33611641, 2021). "In addition, other checkpoints have also been knocked out through gene editing technology to improve the anti-tumor activity of CAR-T cells, such as CTLA-4, TIM-3, and LAG-3." (PMID 33728333, 2021). "We found different tumor purities, immune scores, stromal scores, fractions of different immune cells, expression of several HLA genes and expression of five immune checkpoint molecules (CTLA4, CD274, HAVCR2, LAG3 and TIGHT) among UCEC subtypes." (PMID 34368124, 2021). "However, combination blockade with anti-LAG3 and anti-PD1 dramatically increased viral and tumor clearance." (PMID 33919570, 2021). "Moreover, CDCA7 was significantly correlated with tumor-related immunosuppressive molecules including PDCD1, CD274, CTLA4, BTLA and LAG3." (PMID 33648519, 2021). "The result shows that in tumor cells, PMEPA1 were negatively correlated with some chemokines (including CXCL1, CXCL11, CXCL2, CXCL8, CX3CL1) and positively correlated with CXCL14 and LAG3." (PMID 34777336, 2021).
tumor (continued). "Most recently a study found that whilst the immune phenotype of pleural fluid cells had no prognostic significance, the presence of PD-1 + /LAG-3 + /TIM-3 + CD4 + tumor-infiltrating lymphocytes in pleural biopsy samples correlated with worse overall survival." (PMID 33952230, 2021). "Contact-dependent mechanisms utilizing CTLA-4, lymphocyte-activation gene 3 (LAG-3), and T cell immunoglobulin and ITIM domain (TIGIT) prevent activation and maturation of dendritic cells (DCs) thus preventing an effective anti-tumor T cell response." (PMID 34177968, 2021). "LAG3 and FGL1 play significant roles in tumor therapy resistance." (PMID 35111155, 2021). "LAG-3 expression was assessed in TILs within both the tumor front and tumor center and scored as either positive or negative." (PMID 34442393, 2021). "Therefore, we harvested tumors and spleens from BALB/cJ mice before the first treatment and we looked at the expression of PD-1, PD-L1, TIM-3, and LAG-3 on CD4 and CD8 effector lymphocytes in the spleen as well as on tumor infiltrating lymphocytes (TILs)." (PMID 33466653, 2021). "The mechanisms by which HIF-1 suppresses the function of effector T-cells are complex, but include the upregulation of co-inhibitory receptors (e.g., CTLA-4 and LAG-3), the differentiation of CD4+ T-cells into Tregs and the indirect effect of altered tumour cell metabolism." (PMID 33923305, 2021). "For example, in a syngeneic model utilising an aggressive SCC cell line (KRS-SCC), CD8+ tumour-infiltrating lymphocytes were demonstrated to be over-activated and “exhausted” with notable co-expression of PD-1 and LAG-3, but not CTLA-4." (PMID 33809369, 2021). "IMP321 (a sLAG-3-Ig agent) was the first LAG-3 based molecule in clinical trials and has been combined with vaccination and chemotherapy strategies to try and elicit anti-tumor responses as an apparent immune agonist." (PMID 34068762, 2021). "In MIBC, the high expression of LAG3 may induce the secretion of more inhibitory cytokines, including IL-10 and TGF-β, which inhibit tumor contexture and promote tumor immune escape." (PMID 35111155, 2021). "CYT levels were significantly associated with tumor immune response factors, such as CD19, CD86, LTA, HLA-B, LAG3 and A2AR, in primary tumors but not in metastatic sites (lower row)." (PMID 33476333, 2021). "LAG3 was overexpressed in higher tumor stages compared with stage I, although not significant in stage IV." (PMID 34267742, 2021). "Central memory (Tcm) and effector memory (Tem) CD4pos and CD8pos T cells displayed reduced levels of T cell exhaustion and inhibitory markers such as LAG3, CTLA4 and PD-1, consistent with improved function of memory CD4pos and CD8pos T cell populations in Osm−/− tumours." (PMID 34921158, 2021). "Thus, disrupting the LAG-3/MCH II interaction with blockade therapy should encourage immune activation and anti-tumor responses." (PMID 34268109, 2021). "It remains to be determined whether tumor-infiltrating ILC express LAG-3 and, if so, what the consequences of LAG-3 expression are on ILC function, patient prognosis and therapeutic responses." (PMID 34885076, 2021). "In a study carried out on 163 STS-affected patients, it was found that the frequency of CD8+ and CD4+ T lymphocytes expressing LAG3 is higher than in healthy controls; moreover, the expression is correlated with the presence of TILs CD8+, with a severe prognosis and advanced tumor stage." (PMID 34207243, 2021). "Besides, co-blockade of the LAG-3 and PD-1 pathways in chronic LCMV exhibited robust and synergistic reversal of T cell exhaustion, with similar results in tumor systems and other infection models." (PMID 34434188, 2021). "Tim-3, LAG3, BTLA and CD160 were expressed by a mean of <2% of tumor-infiltrating CD8 T cells, and while CD244 (2B4) was present on higher numbers of CD8 T cells in cSCC, the frequencies of CD244+CD8 T cells did not significantly differ between cSCC, NS and blood." (PMID 33479027, 2021).